MMP9 (matrix metallopeptidase 9)
Diseases named in the same sentence as MMP9 in open-access papers (continued):
Sharing a sentence is not in itself a finding about the gene and the disease.
depression (63 papers, 2009 to 2026). "MMP-9 has been linked to conditions including dementia, post-traumatic stress disorder, bipolar disorder, and depression." (PMID 39997037, 2025). "Multivariate analysis identified PD-1 (OR = 3.32) and MMP-9 (OR = 2.18) as independent risk factors for depression, while IL-10 (OR = 0.62) and BDNF (OR = 0.12) emerged as protective factors." (PMID 40823578, 2025). "Its aberrant elevation has been strongly linked to depression, and minocycline—a tetracycline antibiotic and MMP-9 inhibitor—has been proposed as a therapeutic agent for depressive symptoms." (PMID 41323994, 2025). "Mendelian randomization (MR) analysis using genome-wide SNP data confirmed a potential causal link between MMP9 expression and depression, reinforcing its role as a therapeutic target." (PMID 41323994, 2025). "The results of the present study show that the expressions of autophagy‐related genes (Fkbp5, Mmp9, and Map1lc3b) were increased in the hippocampus of a mouse model of depression that exhibited weight loss." (PMID 39715728, 2025). "This study aimed to characterize anxiety and depression-like behaviors in transgenic MMP-9 mice, as well as the expression of different neuroplasticity markers associated with depression, in both sexes." (PMID 40405318, 2025). "Specifically, some studies indicate that the expression of the matrix metalloproteinase 9 (MMP-9), one protein implicated in neuroplasticity, is increased in patients with depression, and these levels are reduced after antidepressant treatment." (PMID 40405318, 2025). "The activation of the sympathetic–adrenal medullary and hypothalamic–pituitary–adrenal axes is directly related to the association between the polymorphism of the MMP-9 gene and the state of depression in people experiencing chronic stress." (PMID 38254696, 2024). "While a recent meta-analysis did not report MMP-9 elevations in other psychiatric conditions, others implicated MMP-9 in, e.g., depression, bipolar disorder, or posttraumatic stress disorder." (PMID 38431757, 2024). "Elevated serum MMP-9 levels during the acute phase of ischemic stroke were found to be closely associated with the development of depression 3 months later." (PMID 38020612, 2023). "The C allele and C/C genotype of the C1562T MMP-9 polymorphism increase the risk of depression in midlife, while the T allele lowers this risk." (PMID 35370878, 2022). "Another study revealed a significant association between MMP-9 serum levels and depression symptoms; the patients’ MMP-9 serum levels decreased after the patients underwent a course of electroconvulsive therapy." (PMID 35164330, 2022). "Studies reporting on the GCF and salivary levels of cortisol, MMP (matrix metalloproteinase)-8, MMP-9 showed mixed associations with depression." (PMID 35330865, 2022). "Increased levels of MMP9 have been reported in the blood of patients with major depression and an MMP9 level is associated with depression severity." (PMID 35626632, 2022). "The presence of the T-1702A polymorphism for MMP-9 elevates the risk of recurrent depression for the T allele and T/T genotype, whereas the A allele and A/A genotype decrease this recurrence." (PMID 35370878, 2022). "MMP-9 levels were also found associated with several psychological factors linked with depression in a middle-aged population." (PMID 31172215, 2019). "The role of metalloproteinase 9 in affective disorders (depression and bipolar disorders) is currently investigated, indicating association between MMP-9 level, depression severity and treatment." (PMID 27409603, 2016). "MMP9 has been linked with synaptic plasticity as well as with bipolar disorder and depression." (PMID 40563747, 2025). "Recent studies have indeed linked MMP-9 and the symptomatology of depression." (PMID 35370878, 2022). "Interestingly, MMP9 has been previously been associated with depression and increase in response to antidepressant treatments." (PMID 34848679, 2021).
depression (continued). "The MMP9 T-1702A polymorphism plays a role in the development of depression." (PMID 34660916, 2021). "The same study also found that in subjects bearing another MMP9 gene polymorphism of unknown functionality, namely, −1702 T/A, the T/T genotype or T allele led to increase in risk of recurring depressive disorder, whereas the A/A allele led to lower risks." (PMID 31172215, 2019). "Both NGAL and MMP9 are known to modulate plasticity in the brain and damage to monoaminergic neurons may explain comorbidities including depression that are often associated with UCPPS." (PMID 30517112, 2018). "Interestingly, increased MMP9 in circulation is associated with mood disorders such as depression and bipolar disorder." (PMID 25324715, 2014). "MMP9 may also cause a proBDNF/mBDNF (brain-derived neurotrophic factor) imbalance by influencing the process by which proBDNF is converted into mBDNF, leading to depression." (PMID 38993198, 2024). "However, not only clinical depression, but also elevated depressive symptoms may be associated with inflammation and a dose-response relationship between depressive symptoms and MMP-9 (or other inflammatory markers) has been proposed." (PMID 25153995, 2014). "Meanwhile, matrix metalloproteinase-9 (MMP-9) facilitates extracellular matrix degradation and has been implicated in BBB disruption, peripheral-to-central cytokine trafficking, and depression-related neuroinflammatory processes." (PMID 40823578, 2025). "In the midbrain, the expression levels of Fkbp5 and Mmp9 were significantly higher in CIS‐depression model mice than in control mice." (PMID 39715728, 2025). "Increased MMP-9 expression closely parallels greater depression severity, reinforcing its contribution to maladaptive immune–neural interactions." (PMID 40823578, 2025). "Recent studies suggest a potential role for matrix metalloproteinase 9 (MMP-9) in depression, as it is overexpressed in the plasma of depressed patients and normalizes following chronic antidepressant treatment." (PMID 40405318, 2025). "In the present study, Fkbp5, MMP9, and Map1lc3b mRNA expressions were upregulated in the depression model mice compared with the control mice." (PMID 39715728, 2025). "MMP-9 activity modifies anxiety- and depression-like behaviors, as well as neuroplasticity markers, in female but not in male mice." (PMID 40405318, 2025). "We identified eight signature genes related to both Pueraria and depression, with MMP9, MGAM, and CDK5R1 being of particular importance." (PMID 41323994, 2025). "The study by Li Hogmin also shows that MMP-9 is involved in the altered synaptic transmission mechanisms typical of depression symptoms that create psychosocial distress in affected individuals, making this disease very difficult to manage." (PMID 38254696, 2024). "It’s reported that the downregulation of FTO in the anterior cingulate cortex (ACC) by modulating matrix metalloproteinase-9 (MMP-9) mRNA methylation participates in anxiety- and depression-like behaviors in neuropathic pain." (PMID 38384936, 2024). "The significance of MMP-9 in the process of myelinogenesis and subsequent demyelination observed in cases of depression cannot be overstated." (PMID 38254696, 2024). "MMP-9 levels were found to be correlated with the severity of depression and quality of life in patients, as reported by Yoshida." (PMID 38254696, 2024). "Pre-rehabilitation mRNA expression of MMP-9 was found to be inversely linked to cognitive improvement, whereas baseline VEGF protein level predicted improvement in depression symptoms." (PMID 37371326, 2023). "The study sought to indicate that FTO regulates the participation of MMP-9 in the generation and maintenance of anxiety and depression-like behaviors under NP conditions." (PMID 35634463, 2022). "The six predominant targets (TNFα, ESR1, TLR4, PTGS2, MMP9 and NOS3) have been well documented to associate with depression." (PMID 35626632, 2022).
depression (continued). "In summary, we suggest MMP-9 to be an important factor in depression, not only as a therapeutic target but also as a biomarker in the condition." (PMID 35370878, 2022). "In conclusion, downregulation of FTO in ACC by regulating MMP-9 mRNA methylation level contributes to the occurrence of anxiety- and depression-like behaviors in NP mice." (PMID 35634463, 2022). "Studies have shown that MMP-9 participates in anxiety- and depression-like behaviors in mouse hippocampus in a BDNF-dependent manner." (PMID 35634463, 2022). "Large-scale multicenter studies are still necessary to analyse the role of MMP-9 as a contributor for depression." (PMID 35370878, 2022). "MMP-9 appears to be a target for classical antidepressant treatments and MMP-9 inhibitors possess potential therapeutic effects for depression." (PMID 35370878, 2022). "Some studies showed that MMP-2 and MMP-9 genes had relative lower expression on both mRNA and protein levels in depression." (PMID 36045654, 2022). "Increased MMP-9 expression was considered to be as a compensatory response to reduction of mature BDNF in patients with major depressive disorder." (PMID 35370878, 2022). "An increase in expression of the inflammatory genes NFKβ, MMP9, CCL2 in the cortex, the region most associated with depression, was observed in obese rats." (PMID 34714995, 2021). "We explored and adjusted for relevant variables previously linked to CVD: MMP-2, MMP-9, MMP-14, TIMPS, galectin-3, CRP, metabolic variables, life style variables, depression, and thyroid disease." (PMID 34702365, 2021). "In relation to the cognitive phenotype we observe at the long-term, it is of interest that MMP-2 and MMP-9 activity are downregulated in serum of patients with recurrent depression, where higher MMP-levels were correlated with better cognitive performance." (PMID 33057053, 2020). "In parallel, the associations between hopelessness and IL-6 and CRP, and between depression and CRP and MMP-9 all disappeared after adjusting for health risk behaviors." (PMID 32075162, 2020). "It was also reported that the expression of MMP2 and MMP9 (mRNA and protein concentration) differs in people with recurrent depressive disorders and impaired cognitive functions compared to healthy controls." (PMID 33396569, 2020). "It was also found that the serum levels of MMP-9 were upregulated in patients with BD both during the acute phase and remission of depression." (PMID 31172215, 2019). "MMP-9 levels were also correlated with the severity of depression and the quality of life of the patients." (PMID 31172215, 2019). "In another study, an increased level of MMP-9 was found in the blood of patients with major depression." (PMID 31172215, 2019). "This synaptic and dendritic plasticity is also facilitated by MMP9, which is also elevated in the serum of patients with depression." (PMID 30517112, 2018). "Since it is also known that patients with MDD suffer cognitive impairment even in remission, we examined the correlation between serum levels of proBDNF, mature BDNF, and MMP-9, with clinical variables, including depression and cognition, in patients with MDD." (PMID 22880079, 2012). "While neither proBDNF nor mature BDNF serum levels was associated with clinical variables, there were significant correlations between MMP-9 serum levels and the severity of depression, quality of life scores, and social function scores in patients." (PMID 22880079, 2012). "In depression, univariate analysis highlighted a significant difference in particular for insulin and matrix metallo-proteinase 9 (MMP-9), which was also highlighted by the multivariate approach." (PMID 20161799, 2010). "Our study highlights the sex-dependent role of MMP-9 in anxiety and depression." (PMID 40405318, 2025). "Elevated MMP-9 activity is observed in both DM and depression models." (PMID 40244194, 2025). "Similarly, elevated MMP-9 levels were positively correlated with Hamilton Depression Rating Scale (HAMD-17) scores." (PMID 40823578, 2025).
depression (continued). "Moreover, a better understanding of the role of MMP-9 in the development of a depressive/anxious-like phenotype would help to elucidate the role of this protein in the neurobiology of depression." (PMID 40405318, 2025). "While MMP-9 may exhibit protective roles in specific contexts (e.g., amyloid clearance), its role in COPD-associated depression appears to be predominantly pathogenic." (PMID 40823578, 2025). "Other study showed that depression condition in young patient, levels of serum MMP-9 were increased which might be used as biomarker for bipolar disorder." (PMID 38362105, 2024). "MMP-9 is a crucial determinant of extracellular matrix degradation, which is involved in inflammatory response and neuronal plasticity, and it plays a role in the development of brain injury and depression." (PMID 38020612, 2023). "Elevated levels of serum MMP-9 during depression in young patients may indicate that this phenomenon is a potential biochemical marker for the staging of bipolar disorder." (PMID 35370878, 2022). "Nonetheless, accumulated studies indicate that serum MMP-9 may be a novel therapeutic target and biomarker for depression, although a cautionary note is that blood level of MMP-9 may not directly correlate with brain MMP-9 content." (PMID 35370878, 2022). "MMP2 and MMP9 were targeted by hsa-miR-451a, which was decreased by depression in AD patients." (PMID 36040555, 2022). "MMP-9 mRNA level was higher in patients with depression than in the control group." (PMID 35370878, 2022). "Interestingly, these authors noted a positive correlation between the severity of depression and serum MMP-9 levels in patients with major depressive disorders." (PMID 35370878, 2022). "We further explored whether FTO downregulation in ACC regulates anxiety- and depression-like behaviors through MMP-9/BDNF axis coordination in NP model." (PMID 35634463, 2022). "These evidence support MMP-9 as a pathological mediator in depression." (PMID 35370878, 2022). "The aim of this paper is to provide an updated and comprehensive review regarding the role of MMP-9 in the pathology of depression with an emphasis on the probablility that MMP-9 expression could be a potential biomarker of depression." (PMID 35370878, 2022). "MMP-9 as a potential biomarker for depression—results from clinical studies." (PMID 35370878, 2022). "The authors suggest that the level of expression of MMPs (including MMP9) could be used as markers for depression and somatic diseases." (PMID 34660916, 2021). "And ECM markers such as MMP9 and sICAM1 were also reported to deficit cognitive function in human brain which may result in serious psychiatric disorders such as depressive disorders and bipolar disorders." (PMID 33059753, 2020). "Therefore, it is plausible that the associations of hopelessness with IL-6 and CRP and of depression with CRP and MMP-9, all of which vanished after adjustment for physical and lifestyle factors, are mainly reliant on lifestyle factors." (PMID 26979423, 2016). "Lately, MMP-9 has emerged as a candidate marker of depression." (PMID 25153995, 2014). "Moreover, MMP-9 in plasma was highlighted as one of the strongest markers of major depression when a large protein profiling investigation was performed in order to identify novel biomarkers of psychiatric disorders." (PMID 25153995, 2014). "In the period following a challenge with pathogenic intestinal microbes, MMP-9 knockout mice show an increase in lactobacilli, meanwhile increased MMP-9 activity is associated with intestinal permeability, and the severity of human depression." (PMID 23497650, 2013). "The risk for depression on those with MMP–9 positive is 1.58 times higher than those with negative results, with statistical significance [X2=6,49." (PMID 22567050, 2011). "The proposed mediating factors include impairment in endothelial function that was demonstrated both in bipolar and unipolar depression and, as hypothesized here, possibility the MMP9 system." (PMID 20037727, 2009).
depression (continued). "However, whether MMP-9 in ACC is involved in the occurrence or maintenance of anxiety- and depression-like behaviors caused by NP remains unclear." (PMID 35634463, 2022). "However, whether MMP-9 activity participates in the pathophysiology of depression through perineuronal net remodeling still needs more investigations." (PMID 35370878, 2022). "Therefore, we hypothesized that downregulated FTO in ACC contributes to anxiety- and depression-like behaviors-induced by NP by increasing m6A level of MMP-9 mRNA." (PMID 35634463, 2022). "Self-esteem remained significantly associated with IL-6, CRP, and MMP-9 also after adjustment for hopelessness, vital exhaustion, or depression using dichotomy scale and with marginal significance for IL-6 (p = 0.06) and CRP (p = 0.061) after control for depression using continuous scale." (PMID 26979423, 2016). "In the hippocampus, the expression levels of Fkbp5, Mmp9, and Map1lc3b were significantly higher in CIS‐depression model mice than in control mice." (PMID 39715728, 2025). "Increased MMP-9 levels, and to a lesser extent decreased MMP-2 levels, were documented in the depression group." (PMID 35370878, 2022). "One trial used the Hospital Anxiety and Depression Scale (HADS) scale and measured the disease activity index and serum matrix metalloproteinase (MMP)-9 and trimethylamine N-oxide (TMAO) levels." (PMID 35360658, 2022). "For all measured MMPs (MMP-9, MMP-2, MMP-7) and TIMP-2 in blood, increased gene expression was statistically more significant at the mRNA level in patients with depression as compared to control individuals." (PMID 35370878, 2022). "Indirect evidence that points to the role of MMPs other than MMP9 and MMP3 in long-term synaptic plasticity comes from the studies of long-term depression." (PMID 34440823, 2021). "Notably, lower expression levels of MMP9 and CXCR1 were significantly correlated with higher Hamilton Depression Rating Scale (HAMD) scores, indicating greater symptom severity." (PMID 41696471, 2026). "Through a comprehensive assessment of BBB integrity, neuroinflammatory markers, and depression-like behaviors, we demonstrated that MSC transplantation effectively restored BBB function and attenuated neuroinflammation by inhibiting MMP-9 activity and upregulating Cldn5 and Ocln expression." (PMID 40244194, 2025). "Regarding the role of brain MMP-9 in animal models of depression, we recently reported increased expression and activity of MMP-9 in the hippocampus and cortex of a chronic corticosterone mouse model of depression." (PMID 40405318, 2025). "PD-1 (ρ = 0.58, p < 0.001) and MMP-9 (ρ = 0.49, p < 0.001) also positively correlated with HAM-D scores, further implicating immune exhaustion and blood–brain barrier (BBB) compromise in the pathogenesis of depression in AECOPD." (PMID 40823578, 2025). "The expression of autophagy‐related genes (Atg5, Atg7, Atg12, Becn1, Mmp9, Fkbp5, and Map1lc3b), which are reported to be upregulated in the brains of MDD patients, were examined in the hippocampus and midbrain of control and depression model mice." (PMID 39715728, 2025). "Scoring of binding targets revealed that HRAS, MMP9, and Caspase‐3 could be explored as the dominant targets of GAS for depression treatment." (PMID 37650449, 2024). "Considering the substantial amount of evidence that indicates a direct link between the severity of depression and elevated MMP-9 levels, it is plausible that MMP-9 could be a unique biomarker for depression." (PMID 38254696, 2024). "MMP-9 has negative effects on depression, and a high expression of MMP-9 influences perineuronal net remodeling." (PMID 38254696, 2024). "Other biological mediators related to depression and body composition parameters such as insulin growth factor-1 (IGF-1), tumor necrosis factor alpha (TNF-α), interleukin-8 (IL-8), and matrix metalloproteinase-9 (MMP-9) were also determined." (PMID 38362105, 2024).